APOBEC3G (apolipoprotein B mRNA editing enzyme catalytic subunit 3G)
Description:
DNA deaminase (cytidine deaminase) which acts as an inhibitor of retrovirus replication and retrotransposon mobility via deaminase-dependent and -independent mechanisms. Exhibits potent antiviral activity against Vif-deficient HIV-1. After the penetration of retroviral nucleocapsids into target cells of infection and the initiation of reverse transcription, it can induce the conversion of cytosine to uracil in the minus-sense single-strand viral DNA, leading to G-to-A hypermutations in the subsequent plus-strand viral DNA. The resultant detrimental levels of mutations in the proviral genome, along with a deamination-independent mechanism that works prior to the proviral integration, together exert efficient antiretroviral effects in infected target cells. Selectively targets single-stranded DNA and does not deaminate double-stranded DNA or single- or double-stranded RNA. Exhibits antiviral activity also against simian immunodeficiency viruses (SIVs), hepatitis B virus (HBV), equine infectious anemia virus (EIAV), xenotropic MuLV-related virus (XMRV) and simian foamy virus (SFV). May inhibit the mobility of LTR and non-LTR retrotransposons.
Synonyms: ARCD; ARP-9; CEM15; A3G; MDS019; dJ494G10.1; FLJ12740; bK150C2.7; ARP9; CEM-15
Tractability: Small molecule: a structure with a bound ligand is known; it has a high-quality binding pocket; it belongs to a druggable protein family. PROTAC: UniProt records ubiquitination sites on it; ubiquitination databases record sites on it; its protein half-life has been measured; a small molecule that binds it is known.
Target class: Enzyme; Hydrolase
Gene: Protein-coding gene on chromosome 22 (39,077,059 to 39,087,743, forward strand). Ensembl gene ENSG00000239713.
Subcellular location: Cytoplasm; Nucleus; Cytoplasm, P-body
Subcellular location (Human Protein Atlas): Cytosol; Nucleoplasm
Pathways (Reactome):
Disease: APOBEC3G mediated resistance to HIV-1 infection; Vif-mediated degradation of APOBEC3G
Gene Ontology:
Molecular function: cytidine deaminase activity; identical protein binding; protein binding; RNA binding; zinc ion binding; dCTP deaminase activity; hydrolase activity
Biological process: antiviral innate immune response; defense response to virus; DNA cytosine deamination; innate immune response; negative regulation of single stranded viral RNA replication via double stranded DNA intermediate; negative regulation of viral genome replication; negative regulation of viral process; positive regulation of defense response to virus by host; transposable element silencing; base conversion or substitution editing; cytidine to uridine editing; defense response to symbiont
Cellular component: cytoplasm; nucleus; P-body; ribonucleoprotein complex; apolipoprotein B mRNA editing enzyme complex; cytosol
Genetic constraint (gnomAD): Loss-of-function variants: 44 observed, 51.3 expected, observed/expected ratio (o/e) 0.86, 90% interval 0.67 to 1.1. The upper end of that interval is the gene's LOEUF score, 1.1, which puts it in group 4 of 6, group 1 being the genes least tolerant of losing a copy. Missense variants: 469 observed, 510.29 expected, observed/expected ratio (o/e) 0.92, 90% interval 0.85 to 0.99. Synonymous variants: 156 observed, 183.89 expected, observed/expected ratio (o/e) 0.85, 90% interval 0.74 to 0.97.
Homologues: Orthologues: chimpanzee APOBEC3G (95% identical), macaque APOBEC3G (76% identical), dog APOBEC3Z1 (23% identical). Paralogues in human: APOBEC3B (56% identical), APOBEC3F (49% identical), APOBEC3D (42% identical), APOBEC3A (33% identical), AICDA (21% identical), APOBEC3C (20% identical), APOBEC3H (17% identical), APOBEC2 (16% identical), APOBEC1 (15% identical).
Diseases named in the same sentence as APOBEC3G in open-access papers:
APOBEC3G is named in the same sentence as 70 diseases in open-access papers, as found by Europe PMC text mining. Sharing a sentence is not in itself a finding about the gene and the disease. The quoted sentences say what the papers report.
HIV-1 infection (60 papers, 2005 to 2025). The type species of lentivirus and the etiologic agent of acquired immunodeficiency syndrome (AIDS). "They showed that the small subset of iDC susceptible to HIV-1 infection were deficient in APOBEC3G, and they also noted that APOBEC3G levels increased during maturation, which further reduces susceptibility to infection." (PMID 31708924, 2019). "In CD4+ T cells, the expression APOBEC3G increases with activation, but it translocated to the nucleus, which is compatible with the increase in HIV-1 infection susceptibility." (PMID 31708924, 2019). "Over the last decade, experiments seeking the causes of defined cellular blocks to HIV-1 infection uncovered three new RF genes, APOBEC3G (now considered to be the prototype of a cluster of ∼8 APOBEC3 genes), TRIM5, and Tetherin." (PMID 20808775, 2010). "Furthermore, this study demonstrates that APOBEC3G is a susceptibility gene for HIV-1 infection in a West African population from Burkina Faso." (PMID 26741797, 2016). "In the case of HIV-1 infection, IFNα can itself be regulated by cytokines such as IL-27, and has been implicated in the antiviral actions of activator proteins such as tetherin and APOBEC3G." (PMID 20975956, 2010). "Our findings suggest a significantly higher APOBEC3G expression level in patients with DIR, suggesting the potential role of APOBEC3G in patients with immunological discordance besides its suppressing role in HIV-1 infection." (PMID 36380676, 2022). "In monocytes, APOBEC3A, together with APOBEC3G, represents a potent innate barrier to HIV-1 infection, which diminishes during differentiation to macrophages, resulting in a more susceptible population of target cells." (PMID 33072075, 2020). "On the contrary, maturation of DCs leads to an increased expression and accumulation of LMM APOBEC3G, which then contributes to halting HIV-1 infection." (PMID 31708924, 2019). "For example, the cellular restriction factor APOBEC3G can limit HIV-1 infection by inducing G-to-A hypermutations in nascent viral DNA, and this is counteracted by Vif-mediated and ubiquitin-dependent degradation of APOBEC3G." (PMID 29518929, 2018). "In order to decipher the molecular mechanism regulating this late RT, we explored the role of several key partners of NC, such as Vif, gRNA and the cellular cytidine deaminase APOBEC3G that restricts HIV-1 infection by targeting the RT." (PMID 27273064, 2016). "In humans there are multiple APOBEC3 proteins, and APOBEC3G (hA3G) is the predominant restrictor of HIV-1 infection." (PMID 26253512, 2015). "While a previous report showed that exosomal Apobec3G released by H9 T lymphocyte cells blocked HIV-1 infection, the role of Apobec3 or other HRFs mRNA enwrapped in SE is yet to be determined." (PMID 25407601, 2014). "For example, APOBEC3G can block HIV-1 infection in DCs, and its expression is upregulated by IFNα and LPS." (PMID 21504576, 2011). "More recent work has linked the ability of IFNα to inhibit HIV-1 infection in cell lines with a cellular membrane protein CD317 (tetherin) and known HIV-1 restriction factor APOBEC3G." (PMID 20975956, 2010). "Evidence for IFNα regulation of APOBEC3G as an important intracellular defence against HIV-1 infection is compelling." (PMID 20975956, 2010). "In those cells, APOBEC3G exists as a low molecular-mass (LMM) ribonucleoprotein complex that inhibits HIV-1 infection prior to reverse transcription probably through its RNA binding activity." (PMID 19300495, 2009). "Efforts to overcome the known species-specific blocks to HIV-1 infection of macaques imposed by TRIM5α and APOBEC3G have led to the construction of recombinant HIV-1 strains containing SIV capsid and Vif sequences." (PMID 19436700, 2009). "APOBEC3G (A3G), a deoxycytidine deaminase, is a potent host antiviral factor that can restrict HIV-1 infection." (PMID 18414671, 2008).
HIV-1 infection (continued). "A Vif-insensitive restriction block specified by APOBEC3G molecules present in the form of low molecular weight complexes has been described in cells resistant to HIV-1 infection, such as quiescent lymphocytes, monocytes and more recently DCs." (PMID 17212817, 2007). "A number of cellular proteins have been suggested to inhibit HIV-1 replication in resting cells in vitro, such as Murr1 or APOBEC3G, the latter inhibiting HIV-1 infection at the level of reverse transcription." (PMID 17845727, 2007). "APOBEC3G is an innate restriction factor that inhibits HIV-1 infection as a cytidine deaminase." (PMID 35563460, 2022). "APOBEC3G (A3G) is a cellular protein that inhibits HIV-1 infection through virion incorporation." (PMID 31165049, 2019). "In 2002, a cellular host protein APOBEC3G (apolipoprotein B mRNA editing enzyme, catalytic polypeptide-like 3G) was identified, which was able to inhibit HIV-1 infection in the absence of the virally-encoded protein Vif (virion infectivity factor)." (PMID 27186986, 2016). "However, the research on Vif has finally lead to the identification of APOBEC3G, which opens up a new era in the research field of host restriction factors in HIV-1 infection followed by TRIM5α, Tetherin/BST-2, and SAMHD1." (PMID 23430691, 2013). "However, the overall in vivo efficacy of this potential antiviral strategy remains unclear, as HIV-1 infection is known to reduce APOBEC3G in activated CD4+ T cells, thus potentially limiting the amount that can be trafficked into EVs." (PMID 38399678, 2024). "Moreover, APOBEC3G is one of the critical antiviral factors restricting HIV-1 infection." (PMID 36142362, 2022). "Based on the Vif-APOBEC3G antagonism at the protein level, it is conceivable that creation of proteolysis-resistant APOBEC3G could potentially strengthen the host innate anti-viral response and further inhibit HIV-1 infection." (PMID 18680593, 2008). "Constitutively expressed ISGs regulated by U-ISGF3 included antiviral genes such as BST2, APOBEC3G, MX2 that remained elevated during chronic HIV-1 infection." (PMID 33064743, 2020). "Activation of CD4+ T cells enhances APOBEC3G expression and recruitment into HMM, rendering the cells permissive to HIV-1 infection." (PMID 31708924, 2019). "These include host restriction factors such as APOBEC3G, TRIM5α, Tetherin (also known as BST-2), SAMHD1, and MX2, which have been reported to restrict HIV-1 infection and replication." (PMID 30496280, 2018). "The microarray analysis also showed that HIV-1 infection induced various IFN-stimulated genes (ISGs) including HIV-1 restriction factors such as MX2, APOBEC3G (A3G), BST2, and IFITMs in MDMs." (PMID 30496280, 2018). "Here, we provide an overview of the cell-intrinsic HIV-1 restriction activity of APOBEC3G, SAMHD1, Tetherin, and TRIM5α proteins, focusing on their complex interplay with innate and adaptive immune responses in the context of HIV-1 infection." (PMID 30574147, 2018). "Consistent with a previous study in CD4+ T cell cultures in vitro, WT HIV-1 infection significantly enhanced the mRNA expression of APOBEC3D, APOBEC3F, and APOBEC3G." (PMID 25330146, 2014). "Immune-related genes, including CD4, CCL5, IFN-γ, STAT1, APOBEC3G, CD45, and ICAM-1, in PBMCs act a key role in immune responses against HIV-1 infection, and could, hence, be correlated with CD4 T cell depletion in HIV-1 pathogenesis." (PMID 36380676, 2022). "Both APOBEC3G and APOBEC3F are expressed in cell populations susceptible to HIV-1 infection, whereas APOBEC3B is not normally expressed in lymphoid cells and has been shown to be resistant to HIV-1 Vif." (PMID 31708924, 2019). "In this regard, VitD might also protect against HIV-1 infection through induction of an antiviral response mainly mediated by CAMP and APOBEC3G molecules." (PMID 31550271, 2019).
HIV-1 infection (continued). "APOBEC3G (A3G) belongs to the apolipoprotein B mRNA editing enzyme catalytic polypeptide-like (APOBEC) family of proteins and was initially identified as a potent restriction factor against HIV-1 infection in human CD4+ T cells." (PMID 25762005, 2015). "In other studies, MIP3α was shown to up-regulate the host restriction factor APOBEC3G, which inhibits HIV-1 infection in the absence of the viral protein Vif." (PMID 24205323, 2013). "The prototype of the family, APOBEC3G (or A3G), has been identified on the basis of its ability to inhibit HIV-1 infection in the absence of the Vif protein." (PMID 21966267, 2011). "In contrast to the published study, our results do not support a role for APOBEC3G in the inhibition of HIV-1 infection in quiescent T-lymphocytes." (PMID 19300495, 2009). "Although the precise mechanisms involved in this blockage remain unidentified, a number of cellular factors have been reported as restriction factors to HIV-1 infection in quiescent CD4+ T-cells (reviewed in more detail), including Murr1 and most recently APOBEC3G." (PMID 19300495, 2009). "In contrast to their study, our results do not support a role for APOBEC3G in restricting HIV-1 infection of quiescent unstimulated human CD4+ T-cells." (PMID 19300495, 2009). "By eliminating APOBEC3G from the cytoplasm, Vif prevents APOBEC3G from packaging into the viral particles thus augment HIV-1 infection in "non-permissive" cells." (PMID 18680593, 2008). "In this pilot study, we tested whether APOBEC3G, when it is fused with UBA2, can resist Vif-mediated proteasomal degradation and further inhibit HIV-1 infection." (PMID 18680593, 2008). "Several studies on peripheral blood mononuclear cells (PBMC) have found that APOBEC3G mRNA levels correlate positively with the CD4 count and negatively with the viral load of untreated HIV-1-infected subjects, suggesting that APOBEC3G contributes to the control of HIV-1 infection." (PMID 22479480, 2012). "We recently reported that during chronic, untreated HIV-1 infection, IFN-I inducible antiretroviral genes APOBEC3G, BST2 and MX2, as well as IFNβ, but not IFNα, were expressed to significantly higher levels when compared to HIV-1 uninfected individuals." (PMID 33064743, 2020). "Although HIV-1 replication is restricted by APOBEC3G/APOBEC3F, TRIM5α, and CD317, none defend HIV-1 infection under natural conditions." (PMID 19344514, 2009).
viral infection (31 papers, 2006 to 2025). "In HTLV-1, the G-to-A hypermutation is known to be induced at the reverse transcription of the viral genome by the host enzyme Apobec3G, which contributes to host defenses against viral infection." (PMID 39080643, 2024). "Strikingly, this pattern of human APOBEC3G versus human APOBEC3F expression exactly matched the results obtained upon virus infection." (PMID 19371434, 2009). "In summary, our findings indicate that human APOBEC3G is induced upon viral infection as a part of the antiviral response mediated by type I IFN." (PMID 19371434, 2009). "The involvement of the viral infection response, along with interferon signaling and secretion and APOBEC3G degradation denotes the induction of an inflammatory response accompanied by DNA damage; the HIV infection node shared a common edge with the DNA damage and repair gene sets." (PMID 24435511, 2014). "This suggests that IFNβ, expressed upon virus infection in an NF-κB dependent manner, may be an indirect trigger of human APOBEC3G expression, leaving still open the question about the initial viral inducer." (PMID 19371434, 2009). "In this report we demonstrated, proof of principle, a plausible strategy that could be used to stabilize APOBEC3G and to further reduce viral infection." (PMID 18680593, 2008). "In the case of APOBEC3G for example, activation of resting T cells induces the shift of the active low-molecular-mass form of APOBEC3G to an inactive high-molecular-mass complex unable to restrict viral infection." (PMID 16412247, 2006). "Indeed, many HIV-1 antiviral factors are involved in the NF-κB innate signaling pathway by mediating NF-κB-dependent immune responses (i.e., TRIM5α, Tetherin), or responding to NF-κB (i.e., APOBEC3G), or controlling viral infections and inflammatory diseases (i.e., SAMHD1)." (PMID 32595622, 2020). "For example, one module contains APOBEC3G (apolipoprotein B MRNA editing enzyme, catalytic polypeptide-like 3G), which is known to play important roles in adaptive and innate immunity and has been investigated extensively in viral infection but its role in breast cancer remains unclear." (PMID 25505134, 2015). "In a previous EPF genome-wide expression study (GWES), several genes involved in the early stages of viral infection were overexpressed in patients with the generalized form of EPF compared to healthy individuals, including IFITM3, APOBEC3A, APOBEC3G, OAS1, OASL, SERINC3, and RPLP2." (PMID 35632621, 2022). "Vif induces degradation of APOBEC3G, a potent inhibitor of the HIV reverse transcription process; therefore, PAP restores APOBEC3G levels, facilitating its proper functioning as a protective factor against viral infections." (PMID 34194504, 2021). "In order to learn if Csy4 affected viral infection through the host defense system, we used RT-qPCR to quantitate the expression of interferon α2, α6, and two host viral restriction factors (APOBEC3F and APOBEC3G)." (PMID 26495836, 2015). "However, during viral infection of cells, such as HIV-1 (Vif) infection of T lymphocytes, APOBEC3G gains access to viral particles through a ribonucleoprotein interaction and thus APOBEC3 binding to RNA is a critical for antiviral function." (PMID 23890083, 2013). "Thus, the importance of PPARγ, APOBEC3G and IFITM3 upon viral infection could not be denied due to their involvement in pathways affecting viral pathogenicity, specifically in viral replication." (PMID 38263024, 2024).
AIDS (12 papers, 2008 to 2023). A syndrome resulting from the acquired deficiency of cellular immunity caused by the human immunodeficiency virus (HIV). "Lower levels of APOBEC3G mRNA in HIV-infected persons are associated with an increased risk of progression to AIDS, while high levels of APOBEC3G mRNA causes a slow HIV disease progression." (PMID 37376660, 2023). "Studies on host factors, particularly the APOBEC3G gene, have previously found an association with AIDS progression in some populations and against some HIV-1 strains but not others." (PMID 26741797, 2016). "Here, we provide direct evidence that APOBEC3G has functioned as a barrier to cross-species transmission, selecting for viral resistance during emergence of the AIDS-causing pathogen SIVmac in captive colonies of Asian macaques in the 1970s." (PMID 24098115, 2013). "Human apolipoprotein B mRNA-editing enzyme catalytic polypeptide-like 3G (APOBEC3G; A3G), a cytoplasmic DNA cytosine deaminase, is known as a restriction factor that inhibits the replication of human immunodeficiency virus type 1 (HIV-1), the causative agent of AIDS." (PMID 26491161, 2016). "The arms race between lentiviruses and their hosts manifests in our fight against HIV/AIDS as HIV-1 viral infectivity factor (Vif) and host APOBEC3G (A3G) evolve to take control of each other." (PMID 36598981, 2023).